TNF (tumor necrosis factor)
Diseases named in the same sentence as TNF in open-access papers (continued):
Sharing a sentence is not in itself a finding about the gene and the disease.
Cerebral ischemia (continued). "Treatment with melatonin could suppress the levels of IL-6, TNF-α, and IL-1β in animal models of brain ischemia/reperfusion injury, subarachnoid hemorrhage, and traumatic brain injury." (PMID 34685627, 2021). "Report suggests that the TNF-α is activated during the brain ischemia." (PMID 34795593, 2021). "Therefore, suppressing the TNF-α and IL-1β expression is effective for inhibiting cell death following cerebral ischemia." (PMID 32742603, 2020). "Similar studies have shown that cannabinoids inhibit inflammatory TNF activity, indicating that TNF/TNFR1 signaling may contribute to neurodegeneration after cerebral ischemia." (PMID 32528961, 2020). "Results of the present study showed that cerebral ischemia and reperfusion could trigger inflammatory responses that manifested in increasing pro-inflammatory cytokines such as TNF-α and IL-1β." (PMID 32742603, 2020). "Two hours after cerebral ischemia, the expression levels of TNF-α and IL-1β were increased." (PMID 32922507, 2020). "It was reported that OXA pre-treatment could significantly downregulate the mRNA of TNFα and IL-6 in a model of cerebral ischemia, which meant the neuroinflammation was suppressed." (PMID 32539736, 2020). "In a middle cerebral artery occlusion mouse model, irisin was reported to protect against cerebral ischemia-induced neuronal injury by reducing oxidative stress, suppress inflammation by reducing plasma TNFα and IL-6, inhibit the activation of Iba1+ microglia, and infiltrate MPO-1+ monocytes." (PMID 33096842, 2020). "Cerebral ischemia may damage cell membranes of neurons and glial-cells, leading to the release of TNF-α, IL-1β, and IL-6." (PMID 32848589, 2020). "Additionally, the impairment of insulin signaling in the gastrocnemius muscles was noted in rats with cerebral ischemia, with propranolol improving the impairment by reducing oxidative stress and tumor necrosis factor-α signaling." (PMID 32492962, 2020). "Thus, the aim of this study was to evaluate the role of L-Ala-Gln to protect against brain ischemia-reperfusion injury in a gerbil model evaluated through immunohistochemistry (IHC) for the IL-6, TNF-α, NF-κB and HO-1." (PMID 32696813, 2020). "In this study, we evaluated the nose-to-brain delivery of siRNA targeting TNF-α (siTNF-α) conjugated with PEG-PCL-Tat to investigate its therapeutic effects on a transient middle cerebral artery occlusion (t-MCAO) rat model of cerebral ischemia-reperfusion injury." (PMID 31540164, 2019). "Moreover, our results clearly demonstrate that PEA-OXA treatment downregulated the IL-1β, TGF-β, and TNF-α expression induced by cerebral ischemia." (PMID 31569558, 2019). "Moreover, inhibition of Cox-2 during neuroinflammation induced by traumatic brain injury, cerebral ischemia, and TNF-α challenge attenuates BBB disruption, possibly by reducing levels of PGE2." (PMID 31779628, 2019). "Moreover, M8I inhibited microglial activation and TNF-α expression in the brain of mice with systemic inflammation and cerebral ischemia, corroborating the findings through MMP-8 knockdown experiments." (PMID 30470240, 2018). "Inflammatory responses (such as the release of proinflammatory cytokines interleukin-1 β (IL-1β), IL-6, and tumor necrosis factor (TNF-α)) increase the expression of adhesion molecules in white blood cells and vascular endothelial cells after brain ischemia and reperfusion." (PMID 29540536, 2018). "The NF-κB activity and enhanced TNF-α expression could be attributed to an apoptotic pathway following global cerebral ischemia." (PMID 29021761, 2017). "To investigate whether adjudin-pretreated NSCs in the acute phase of cerebral ischemia had a better effect on immunomodulatory influence, we first examined IL-6, IL-1β, and TNF-α mRNA expression in both the cortex and the striatum." (PMID 29115993, 2017). "Following brain ischemia, expression of TNF-α increases in the ischemic penumbra." (PMID 28957432, 2017).
Cerebral ischemia (continued). "This suggests that TNF-α induction post-cerebral ischemia may be instrumental in promoting expression of the α5β1 and αvβ3 integrins as part of the angiogenic process." (PMID 27586239, 2016). "The immune response generated in this context, dominated by IFN-γ and TNF-α, may facilitate vessel contraction and increase the vulnerability of the brain to cerebral ischemia." (PMID 27115869, 2016). "TNF-α is another proinflammatory cytokine involved in cerebral ischemia-reperfusion injuries." (PMID 28101118, 2016). "TNF-α gradually increases from 1 to 3 h after cerebral ischemia and reaches a peak at 24–36 h." (PMID 28101118, 2016). "Furthermore, there was a significantly decrease in the level of TNF-α mRNA or protein expression both 3 and 7 days after BMSCs transplantation, as compared with the brain ischemia group (both P < 0.05)." (PMID 26931747, 2016). "We concluded that the intravenous transplantation of BMSCs originated from the bone marrow could partially ameliorate lung injury induced by brain ischemia, and inhibited the mobilization of inflammatory cells and reduce the TNF-α protein expression in lung." (PMID 26931747, 2016). "Moreover, both the mean density of TNF-α and the number of the inflammation cells were significantly decreased in BMSCs transplantation group (vs brain ischemia group, P < 0.05)." (PMID 26931747, 2016). "Cerebral ischemia injury involves low-level chronic inflammation, and studies have shown that FcγR could induce TNF-α mRNA expression and MIP-1α production." (PMID 26693244, 2015). "Furthermore, because the plasma concentration of TNF-α was increased after cerebral ischemia, we assessed the cerebroprotective effect of ETN." (PMID 26665003, 2015). "Nevertheless, the inhibitory effects of 6-paradol on iNOS and TNF-α can be applied to other many CNS disorders where these molecules are the main pathogenetic components, such as cerebral ischemia, multiple sclerosis, AD, PD, amyotrophic lateral sclerosis, or spinal cord injury." (PMID 25789481, 2015). "Within the first 24 hours of cerebral ischemia in animal models, inflammatory cytokines interleukin-1β (IL-1β), interleukin-6 (IL-6), and tumor necrosis factor-α are upregulated dramatically by up to 40- to 60-fold and are believed to affect the infarct volume and tissue damage." (PMID 24877133, 2014). "Both TNF-α and IL-1β cytokines are supposed to play crucial roles in inflammatory cells infiltration and glia activation induced by cerebral ischemia, which exacerbate cerebral ischemia-reperfusion injury." (PMID 24707308, 2014). "Whereas TNF-α and IL-1β appear to exacerbate cerebral injury, transforming growth factor-β and IL-10 may exert neuroprotective effects during cerebral ischemia reperfusion." (PMID 25092271, 2014). "This activity is mediated, at least in part, by inhibition of inflammatory responses (i.e., HIF-1α, iNOS expression) and apoptosis (i.e., TNF-α, active caspase-3), resulting in a reduction of infarct volume and improvement in neurobehavior in rats with cerebral ischemia." (PMID 24285977, 2013). "Several cytokines, including TNFα, IL-1 beta, and IL-6 have been shown to participate in cerebral ischemia-induced inflammatory processes, but a complete database including all possible inflammatory mediators remains to be established in cerebral ischemia/reperfusion injury." (PMID 24204940, 2013). "Gene expression of TNF-α and IL-1β, after cerebral ischemia is up-regulated." (PMID 23351182, 2012). "Evidence suggests that pro-inflammatory cytokines such as IL-1β, IL-6 and TNFα may influence the extent of neuronal damage after cerebral ischemia." (PMID 22873409, 2012). "In addition, increased production of TNFα in brain tissue has been reported following cerebral ischemia." (PMID 23259581, 2012). "Differently from TNF-α, IL-18 might act as a delayed mediator of neuroinflammation, in agreement with data obtained in experimental models of brain ischemia and trauma." (PMID 22642744, 2012).
Cerebral ischemia (continued). "During cerebral ischemia, elevation of TNF-α and glutamate to pathophysiological levels may induce dysregulation of normal synaptic processes, leading ultimately to cell death." (PMID 21810263, 2011). "Cytokines that participate in the inflammation after cerebral ischemia include the neurotoxic cytokines interleukin-1β (IL-1β), tumor necrosis factor-alpha (TNF-α), neuroprotective cytokines interleukin-6 (IL-6), interleukin-10 (IL-10) and transforming growth factor-β." (PMID 21740583, 2011). "As expected, TNF-α expression was upregulated following cerebral ischemia." (PMID 22031820, 2011). "In this study, we demonstrated that THSWT can inhibit TNF-α expression during brain ischemia." (PMID 21076527, 2011). "Delayed expression of intercellular adhesion molecule-1 in astrocytes may be regulated by TNF-α and its receptors after brain ischemia." (PMID 21152396, 2010). "In addition, TNF-α is one of the key immunomodulatory and proinflammatory cytokines upregulated during brain ischemia." (PMID 19272172, 2009). "In models of cerebral ischemia, astrocytes exhibit a neuroprotective subtype, whereas under neuroinflammatory conditions, inflammatory microglia are able to induce astrocyte activation into a neurotoxic subtype by secreting three factors, IL‐1β, TNF‐α, and C1q." (PMID 39508266, 2024). "Furthermore, reducing TNF-α activity may represent a potential treatment strategy to prevent cerebral ischemia, possibly through its effects on NF-κB." (PMID 39882206, 2024). "Furthermore, intracerebral ventricular administration of tumor necrosis factor (TNF), an acute-phase proinflammatory cytokine known to be secreted by both microglia and macrophages, dose-dependently increased infarct volume in rodent models of brain ischemia." (PMID 36979460, 2023). "Similarly, in rat models of cerebral ischemia, triflusal conferred a prominent neuroprotective effect through the inhibition of glial activation and suppression of NF-κB-regulated expression of IL-1β, TNF-α and COX-2." (PMID 35631487, 2022). "Therefore, the cerebral ischemia increases MCP‐1 expression in endothelial cells and/or neurons, which causes the activation of microglia, leading to inflammatory response such as increases in IL‐1β and TNF‐α expression, and VCI in small vessel disease." (PMID 34586752, 2021). "In response to brain ischemia, microglia initiate reactive oxygen species generation, antigen presentation, phagocytosis, and the production of inflammatory mediators, including interleukin (IL)-1β, tumor necrosis factor (TNF)-α, IL-6, and matrix metalloproteinases." (PMID 32276642, 2020). "Likewise, previous study manifests that apelin-13 exerts a protective role for neurons against cerebral ischemia/reperfusion (I/R) injury through inhibiting the expression of inflammatory factors (IL-1β, TNF-α, and ICAM-I) and the activation of microglia and astrocytes." (PMID 31040784, 2019). "Cerebral ischemia triggers inflammatory responses and numerous inflammatory mediators that exacerbate ischemic brain injury are induced at the transcriptional level, including enzymes required for prostaglandin synthesis, cytokines (e.g., IL-6 and TNF-α), and chemokines." (PMID 29234386, 2017). "Although such a fundamental alteration could be beneficial in preserving normal hippocampal function under the physiological stress of cerebral ischemia, we found that post-ischemic TNFα-Tg rats showed impaired performance on both cognitive and functional tasks at extended time intervals after MCAO." (PMID 27144978, 2016). "In this study, we firstly explored whether BMSCs transplantation could alleviate inflammatory activities and improve functional consequence in lung injury induced by brain ischemia, then investigated the possible molecular mechanism involving in the expression of TNF-α." (PMID 26931747, 2016).
Cerebral ischemia (continued). "Therefore, BMSCs treatment can reduce lung injury, in which, the possible mechanism may link to the inhibition of TNF-α in brain ischemia induced lung injured rats." (PMID 26931747, 2016). "Therefore, the neuroprotective effects of 6-paradol in cerebral ischemia might be partly due to reducing expression levels of iNOS and TNF-α in microglia." (PMID 25789481, 2015). "Under cerebral ischemia and anoxia, the activated TLR4 promotes the expression of nuclear factor (NF)-κB and induces the production of cytokines, such as tumor necrosis factor (TNF)-α and interleukin (IL)-6, thereby causing inflammation and neurological injury." (PMID 25187844, 2014). "However the function of TNF in brain ischemia is controversial." (PMID 21810263, 2011). "In a study of blood mononuclear cells from patients with cerebral ischemia, increased expression of circRNA HECTD1 in these cells was demonstrated, which correlated with blood levels of TNF-α, IL-6, and IL-1β." (PMID 41245147, 2025). "The KEGG results indicated that 15 pathways were closely related to cerebral ischemia, including the VEGF signaling pathway, estrogen signaling pathway, TNF signaling pathway, apoptosis, and so on." (PMID 40869300, 2025). "In mice with cerebral ischemia and reperfusion, brain TNF signaling pathway was activated by reperfusion, and inhibiting TNF‐α with adalimumab significantly attenuated reperfusion‐induced brain endothelial inflammation." (PMID 37789643, 2024). "Activation of microglia leads to the release of inflammatory cytokines such as nitric oxide (NO), tumor necrosis factor (TNF)-α, and interleukin (IL)-1β, characteristic markers of AD, PD, MS, and cerebral ischemia." (PMID 39595080, 2024). "It was demonstrated that taVNS inhibited the expression of interleukin (IL)-1β, IL-6, and tumor necrosis factor-α (TNF-α), and promoted the functional recovery of cerebral ischemia/reperfusion-injured rats." (PMID 39444545, 2024). "Tumor necrosis factor-alpha (TNF-α) is a pro-inflammatory cytokine involved in neuroinflammation and neuronal damage induced by cerebral ischemia." (PMID 37287803, 2023). "After cerebral ischemia, the NF-κB pathway extends the inflammatory response in the brain, activating inflammatory signals such as iNOS, COX-2, IL-1β, TNF-α, IL-6, and others." (PMID 35838888, 2023). "In the cerebral ischemia-reperfusion model used to study it, SYR, like other compounds, reduced the expression of NF-κB, IL-1β, IL-6, and TNF-α." (PMID 38813032, 2023). "HS treatment significantly decreased the levels of NF-κB, TNF-α, IL-6, MDA, and Caspase-3 and markedly demonstrated protection with respect to cerebral ischemia-reperfusion in rats." (PMID 37371417, 2023). "Acupuncture at Neiguan and Dazhui points can significantly reduce the expression of TNF-α and NF-κB-p65 in the ischemic hippocampal CA1 region, thereby reducing cerebral ischemia injury." (PMID 36091595, 2022). "Another alakaloid, l-Tetrahydropalmatine, exhibited cardioprotective effects against acute global cerebral ischemia-reperfusion injury by activating the PI3K/Akt/eNOS/NO pathway and decreasing the accumulation of inflammatory factors, such as TNF-α and MPO." (PMID 35888597, 2022). "It has been seen that IL-6 and TNF-α increase significantly in cerebral ischemia and inhibiting the IL-6 and TNF-α pathways can alleviate cerebral ischemia injury." (PMID 36142849, 2022). "RvD1 ameliorated neuronal death, decreased IL1β, TNFα, malondialdehyde, MDA, and NLRP3 protein in rats with cerebral ischemia/reperfusion injury." (PMID 36670960, 2022). "In the cerebral ischemia model test, TNF‐α RNA can be clearly detected after 1 hour, and TNF‐α protein increases after 2–6 hours; thus, TNF‐α responds more quickly during cerebral ischemia." (PMID 33423390, 2021). "Second, we compared the effect of BBR and BBR-loaded micelle on TNF-a, IL-1B (inflammations factors), and MDA (marker of oxidative stress) due to inducing cerebral ischemia in the rat." (PMID 34600570, 2021).
Cerebral ischemia (continued). "Cerebral ischemia activates innate immune receptors on microglia/macrophages and other cells resulting in the release of cytokines and chemokines such as IFN-γ, TNF-α, and IL-1α." (PMID 33514001, 2021). "Results indicate factors such as oxygen-free radicals and inflammatory cytokines (such as TNF-α, IL-1ß) and Malondialdehyde (MDA) as a marker of oxidative stress that plays an important role in damaging brain tissue and neurons due to cerebral ischemia." (PMID 34600570, 2021). "Electroacupuncture alleviates cerebral inflammation in cerebral ischemia/reperfusion injury through the TLR4/NF-κB pathway, which is accompanied with the suppressed secretion of the inflammatory cytokines TNF-α, IL-1β and IL-6." (PMID 32479555, 2020). "Pre-treatment of CFT attenuates proinflammatory cytokines, such as Nuclear Factor-κB, interferon-γ, and/or tumor necrosis factor-α (TNF-α) and interleukin-1β (IL-1β) in various neurological models of PD neuropathy, TBI and cerebral ischemia." (PMID 32456229, 2020). "Irisin reduced oxidative stress-induced neuronal damage by inhibiting the secretion of proinflammatory cytokines, such as tumor necrosis factor α (TNFα) and IL-6, by the Akt/ERK1/2 signaling pathway in the mouse model of cerebral ischemia (MCAO)." (PMID 31443222, 2019). "Reperfusion after cerebral ischemia (R/I) in MetS rats increased MDA, TNF-α, and IL-6 levels, but it decreased the activities of the main scavenger enzymes including SOD, CAT, and GSH-Px and neuron densities in CA2 and CA3 subregions of the hippocampus." (PMID 30937145, 2019). "TNF-α, IL-6, MCP-1, VEGF, and MMP expression induced by cerebral ischemia was abrogated in Poldip2+/− mice." (PMID 29452577, 2018). "In the animal model of cerebral ischemia, circulating HMGB1 acting via the receptor of advanced glycation end-products (RAGE) was responsible for the reduced secretion of TNFα and IL-12 by monocytes and lymphopenia." (PMID 29669581, 2018). "Among them, TNF-α, IL-1β and IL-6, iNOS and COX-2 are all dynamically altered in different stages of brain ischemia-reperfusion, and they usually bring detrimental effect to brain and BBB." (PMID 30622459, 2018). "IL-1β also has a synergistic effect with TNF-α to further exacerbate brain damage and cerebral ischemia can upregulate TNF-α and participate in the pathological process of brain injury, while TNF-α can promote the release of IL-1β and other cytokines." (PMID 28491108, 2017). "Pan-PDE4 inhibitors, such as rolipram, have been used to reduce tumor necrosis factor (TNF) levels and neutrophil accumulation in models of systemic inflammation and CNS injury, such as SCI, cerebral ischemia and TBI." (PMID 28542295, 2017). "Similar results were obtained from PEMF exposure after brain ischemia, which indicated that PEMF influences neuroinflammation via elevation of anti-inflammatory IL-10 and reduction of pro-apoptotic tumor necrosis factor." (PMID 28220060, 2017). "TCMs effectively ameliorate cerebral I/R injury by downregulating TLR4, TNF-α, IL-1β, IL-6, iNOS, COX-2, and 5-LO expression and upregulating IL-10 expression in the ischemic area during the acute and subacute phases of cerebral ischemia." (PMID 27703487, 2016). "Moreover, BMSCs may regulate TNF-α expression in brain ischemia induced lung injury." (PMID 26931747, 2016). "RT-PCR analysis indicated that TNF-α, IL-1, ICAM-1, and MMP-9 mRNA levels were elevated and suggested that NF-κB was activated by ROS produced during the 14-min global brain ischemia and 24-h reperfusion injury." (PMID 26230326, 2015). "Meanwhile, as target genes of NF-κB, several pro-inflammatory cytokines and enzymes, such as TNF-α, IL-1β and cyclooxygenase (COX)-2 are upregulated and lead to neuronal damage after cerebral ischemia." (PMID 23997755, 2013). "On the other hand, pentoxifylline reduced brain edema in a rat model of transient focal cerebral ischemia through a decline in TNF-α production, suggesting an deleterious role of TNF-α." (PMID 23431245, 2013).